NRG1 (neuregulin 1)
Diseases named in the same sentence as NRG1 in open-access papers (continued):
Sharing a sentence is not in itself a finding about the gene and the disease.
schizophrenia (continued). "Until now, besides NRG1 rs6994992, the associations between other schizophrenia risk variants and creativity have not yet been explored, and it is therefore still unknown whether there have been other schizophrenia risk variants that underlie the genetic link between schizophrenia and creativity." (PMID 31649580, 2019). "As reviewed here, some of the genetic animal studies, such as NRG1/ErbB4 and 14-3-3 animal models, provided evidence to support NMDAR hypofunctionality as a potential convergence point for symptoms of schizophrenia." (PMID 31417356, 2019). "Since prefrontal cortex is one of the most schizophrenia-related regions, we took it as an example to examine the possible effects of DMS on NRG1-ErbB4 signaling in the brain." (PMID 30574102, 2018). "Nrg1 TM HET mice also exhibit face and predictive validity for schizophrenia, as they display behavioural features relevant to the symptoms of schizophrenia, some of which can be ameliorated by antipsychotic treatment." (PMID 29467679, 2018). "NRG1, a member of NRG family, is known as a key growth factor for the development of the normal nervous system and the occurrence of schizophrenia, which is also involved in cancer progression." (PMID 30486894, 2018). "Taken together with previously published NRG1 results, our findings suggest an overall upregulation of transcripts within the NRG–ErbB signaling pathway among individuals with schizophrenia some of which attenuate over duration of illness." (PMID 29163244, 2017). "Though data from computational pathway analyses have implicated interactions between NRG1 and Src signaling pathways which play roles in both schizophrenia and T2D, to date, the links between NRG1 and the metabolic disturbances intrinsic to schizophrenia are not well-established." (PMID 28804444, 2017). "Regarding investigation of the relationship between NRG1 gene and ERP in schizophrenia, a study found a significant linkage between SNP8NRG221533 and P300 latency, showing individuals carrying more C alleles had greater P300 latency delay." (PMID 28993723, 2017). "In addition, associations between genetic variation in the GSK-3 gene and schizophrenia (SZ) have been reported and a number of other susceptibility genes for SZ, including the genes encoding for the proteins disrupted in SZ (DISC1), neuregulin 1 (NRG-1), and dysbindin converge on GSK-3 signaling." (PMID 29375364, 2017). "While changes in Nrg1 expression levels in schizophrenia still remain controversial, understanding the BACE1-cleaved Nrg1-ntf and Nrg1/ErbB4 signaling in schizophrenia neuropathogenesis is essential and important." (PMID 28993723, 2017). "When gene expression by PCR arrays was analyzed exclusively in the medial rectus samples, we found that three schizophrenia-related genes were significantly altered: NPY1R, NRG1, and NTRK2 (adjusted p ≤ 0.012500)." (PMID 29302405, 2017). "Differential expression of neuregulin-1 (NRG1) mRNA isoforms and proteins has been reported in schizophrenia, primarily in post-mortem brain tissue." (PMID 29225331, 2017). "Decreased spine density in hippocampal pyramidal neurons was also observed in Bace1-/- mice via NRG1/ErbB4 signal pathway regulation, suggesting that disturbed NRG1/ErbB4 signaling pathways in the Bace1-/- mouse model may contribute to the pathophysiology of schizophrenia." (PMID 28993723, 2017). "PI3K-Akt pathway is also the intracellular downstream pathway of glutamate, serotonin, dysbindin, disrupted in schizophrenia-1 (DISC-1), and neuregulin 1 (NRG1), which are all the targets for mood stabilizers and antipsychotic drugs." (PMID 29156812, 2017). "Kalirin-7 also interacts with genetic factors for schizophrenia (e.g., DISC1, NRG1) in regulating dendritic morphology and spine plasticity." (PMID 28036092, 2016).
schizophrenia (continued). "Candidate genetic factors for schizophrenia, including disrupted in schizophrenia 1 (DISC1), neuregulin-1 (NRG1), and dysbindin, have distinct roles in synapse-specific mechanisms and directly affect functional signaling involved in synaptic transmission." (PMID 28036092, 2016). "The Neuregulin 1 transmembrane domain heterozygous mutant (Nrg1 TM HET) mouse is used to investigate the role of Nrg1 in brain function and schizophrenia-like behavioural phenotypes." (PMID 25992564, 2015). "Genetic evidence also supports ERBB4 – the NRG1 receptor – as a candidate susceptibility gene and suggests positive epistatic interactions between NRG1 and ERBB4 in schizophrenia." (PMID 24478629, 2014). "For example, studies of schizophrenia have revealed synergistic SNP-SNP interactions in dopamine receptor D4 (DRD4) and in neuregulin 1 (NRG1)/v-erb-a erythroblastic leukemia viral oncogene homolog 4 (avian) (ERBB4)/AKT1 genes." (PMID 24955105, 2014). "Conversely, deletion of the Aph1bc-γ-secretase complex does not affect Notch signalling but hampers Nrg1 processing and alters sensory motor gating, working memory and sensitivity to psychotropic drugs, thereby mimicking Nrg1 deficiency and various phenotypes related to schizophrenia." (PMID 24891237, 2014). "CBD selectively enhanced social behaviour, prepulse inhibition, and retrosplenial GABAA binding in Nrg1 TM HET mice, supporting its potential therapeutic value in treating specific symptoms of schizophrenia." (PMID 22509273, 2012). "NRG1 has neurotrophic activities to promote NMDA receptor expression, GABA synthesis, and myelination, all of which are diminished in postmortem brain of schizophrenia patients." (PMID 21151609, 2010). "However, some caution should be exercised before calling NRG1 a true "schizophrenia gene" due to the lack of a known functional effect of the identified NRG1 variants, the allelic heterogeneity reported across several studies and the multiple SNPs and haplotypes analysed in different studies." (PMID 17598910, 2007). "Notably, neonatal hypoxia has been shown to induce the neurotrophic factor neuregulin-1 (NRG1), and a mouse model of schizophrenia—generated by neonatal administration of NRG1—exhibited hyperinnervation of DA axons in the mPFC but not in the striatum." (PMID 40940759, 2025). "Both NRG1 and ERB-B4 signalling are reportedly increased in the brains of schizophrenia patients." (PMID 38563502, 2024). "Another study showed a connection between C carriers of NRG1 rs35753505 and a decreased expression of the NR2C subunit in the right cerebellum as a compensatory mechanism for the hypofunction of the NMDA receptor of patients suffering from schizophrenia." (PMID 39062492, 2024). "Current study seems to assume a link between enhanced NRG1-ErbB signaling and reduced NMDAR function in PFC could be a debatable topic with respect to schizophrenia." (PMID 36692676, 2023). "The NRG1/ERbB4 and PI3K signaling pathways may offer a new therapeutic approach to developing treatment for schizophrenia in humans, which needs to be assessed in further studies." (PMID 35876932, 2022). "CBD did not alleviate the schizophrenia-relevant hyperlocomotive phenotype of Nrg1 mutants, nor deficits in social behaviors." (PMID 36406747, 2022). "In the present study, NVHL rats, which also exhibit schizophrenia-like behaviors, showed significant reduction in NRG-1 and p-erbB4 levels in the PFC, suggesting that NRG-1/erbB4 pathway in the PFC of NVHL rats was impaired." (PMID 36620856, 2022). "Furthermore, our early work on mice has shown that elevated Nrg1 expression (Nrg1-III-tg) showed ventricular enlargement and symptoms similar to schizophrenia." (PMID 35562880, 2022). "Thus, this study aimed to investigate the effects of aripiprazole and sertindole on the NRG1/ERbB4 and PI3K/AKT/mTOR signaling pathways in ketamine-induced schizophrenia in rats." (PMID 35876932, 2022).
schizophrenia (continued). "Furthermore, NRG1 knockdown in FGR mouse mPFC improved PV interneuron GABAergic maturation and rescued schizophrenia behaviors including hyperactivity, social novelty defects, cognition decline, and sensorimotor gating deficits in FGR mice." (PMID 36460658, 2022). "Although experimental and clinical studies indicate that plasma NRG1 levels are decreased in brain disorders such as schizophrenia or Parkinson’s disease, this seems to not be the case in BD conditions." (PMID 35625715, 2022). "Here we found that, overall, CBD did not reverse schizophrenia-relevant behaviors in Nrg1 mutant mice." (PMID 36406747, 2022). "The NRG1/ErbB4 and PI3K signaling pathways may offer a new therapeutic approach for treating schizophrenia in humans." (PMID 35876932, 2022). "We found that Nrg1 expression was increased in GABAergic interneurons but not in PN from the PFC of schizophrenia patients, compared with age- and sex-matched healthy controls." (PMID 33436636, 2021). "The increased type I Nrg1 expression in GABAergic interneurons from schizophrenia PFC seems not to be due to the antipsychotic treatment because type I Nrg1 mRNA levels were similar between drug-naive and drug-treated schizophrenia patients." (PMID 33436636, 2021). "Of note, the increase of Nrg1 expression in schizophrenia brain did not correlate with antipsychotic treatment, suggesting an association with the disorder instead of medication." (PMID 33436636, 2021). "By contrast, Nrg1 mRNA levels were not significantly altered in PN from schizophrenia PFC, compared to age- and sex-matched controls." (PMID 33436636, 2021). "Two studies also found increased neuregulin 1 expression in post-mortem tissue from prefrontal cortex and hippocampus of schizophrenia patients, although a third did not detect this pattern." (PMID 31824347, 2019). "Thus, the first aim of this study was to clarify the relationship between NRG1 rs6994992, schizophrenia and creativity by validating the association between NRG1 rs6994992 and creativity in healthy subjects of Han Chinese population in which NRG1 rs6994992 is not a schizophrenia risk variant." (PMID 31649580, 2019). "Therefore, the results of this study raised new questions about the role of NRG1 rs6994992 in the relationship between schizophrenia and creativity, and suggested ethnic differences may also exist in the relationship between NRG1 rs6994992, schizophrenia and creativity." (PMID 31649580, 2019). "Moreover, it has been demonstrated that NRG1 also regulates DISC1 expression, thus further worsening the aberrancy of the Akt–mTOR pathway and the pathogenesis of schizophrenia and related behaviors." (PMID 30061532, 2018). "Additional proteins implicated in risk for schizophrenia, but that have not yet been reported to affect LTD, interact with this pathway either as upstream activators (e.g., NRG1) or as transcriptional regulators (e.g., EGR1 and NAB2)." (PMID 29520222, 2018). "Future studies comparing NRG1 gene and protein expression between treatment-resistant and non-resistance schizophrenia patients, including treatment-naive patients, are warranted." (PMID 29225331, 2017). "PCP induced alterations in mRNA expression encoding schizophrenia-related genes, such as NR2A, NR2B, neuregulin 1, NR1 and GABA α1 subunit were absent in the PFC of young adult P2rx7−/− animals." (PMID 27824163, 2016). "Finally, several groups have assessed gene expression and proteins of NRG1 and ERBB4 in postmortem brains and have reported differences between schizophrenia and healthy control groups." (PMID 24478629, 2014). "Interestingly partial genetic deletion of Nrg1 hypophosphorylates NR2B subunits of NMDARs and promotes subtle changes in NMDAR binding in a number of schizophrenia relevant brain regions in adult rodents." (PMID 25324742, 2014). "Indeed, these human studies were the impetus for our research on animal modeling of schizophrenia using EGF and NRG1." (PMID 24949465, 2014).
schizophrenia (continued). "Accumulating evidence suggests that neuregulin 1 (NRG1) might be involved in the neurodevelopment, neural plasticity, GABAergic neurotransmission, and pathogenesis of schizophrenia." (PMID 24782733, 2014). "Gene-gene interaction between NRG1 and NRG3 has also been observed in a schizophrenia study, and according to the NCBI BioSystems database, NRG3 may also be involved in the immune system." (PMID 25919455, 2014). "This cytokine-driven dopaminergic dysfunction might illustrate some of the psychopathological features of schizophrenia, although it is possible that the responsible factor(s) might be other cytokines other than EGF, NRG1, or virokine." (PMID 24949465, 2014). "Importantly, Nrg1 can interact with BDNF in regulating neuronal processes, BDNF down-regulation has been reported in schizophrenia, and BDNF expression changes impact on the sensitivity to social defeat stress." (PMID 23966917, 2013). "In addition, decreased gene expression of NRG1 and dystrobrevin binding protein 1 (DTNBP1) were shown to be lower in immortalized lymphocytes from patients with schizophrenia vs. controls before and after treatment with the antipsychotic olanzapine." (PMID 23805071, 2013). "Between-gene interactions including DAO*DISC1,DAO*NRG1 and DAO*RASD2 and a within-gene interaction for CACNG2 were found among schizophrenia subjects with severe sustained attention deficits, suggesting a modifying effect of impaired neuropsychological functioning." (PMID 23555897, 2013). "Additionally, phosphorylation of Erbb4 by NRG1 and downstream AKT and ERK2 signalling are more likely to be activated in schizophrenia, compared to control samples." (PMID 23301017, 2013). "Several other studies have revealed that the disruption of NRG1-ErbB4 signalling leads to dysfunction in neuronal migration, NMDA hypofunction and regulation of GABAergic neurotransmission that are also disrupted in schizophrenia." (PMID 23301017, 2013). "CBD did not alter schizophrenia-relevant behaviors such as hyperlocomotion or PPI deficits in our Nrg1 HET mouse model." (PMID 23447438, 2013). "A review on the role of Nrg1 in GxE in schizophrenia would be incomplete without mentioning the extensive mouse work on Nrg1 x cannabis interactions." (PMID 23966917, 2013). "Here we investigated whether Nrg1 TM HET mice respond differently to CBD and whether CBD reverses schizophrenia-related phenotypes expressed by these mice." (PMID 22509273, 2012). "Cannabidiol did not reduce the expression of schizophrenia-relevant behaviors in Nrg1 TM HET mice." (PMID 36406747, 2022). "However, there are contradictory findings reported in the literature; one study reported elevated cleavage of neuregulin-1 by β-secretase (BACE1) in the plasma of patients with schizophrenia and a relationship between BACE1-cleaved-NRG1 activity and both disease severity and disease duration." (PMID 35337293, 2022). "There is no sex difference for type I Nrg1 expression in the schizophrenia PFC." (PMID 33436636, 2021). "Some papers reported that more homozygous Val/Val in catechol-O-methyltransferase (COMT) Val158Met genotypes were found (31 vs. 17%) in the non-deficit schizophrenia patients compared to the deficit schizophrenia subgroup, and SNP8NRG241930 in NRG1 were associated with non-deficit schizophrenia." (PMID 29156812, 2017). "As such our results suggest that NRG1 overexpression may not be restricted to the brain of those with schizophrenia, and blood-based NRG1 transcription may serve, in part, as a suitable biomarker for schizophrenia and perhaps treatment-resistant schizophrenia." (PMID 29225331, 2017). "Considering the clinical relevance of deficits in NRG1 and DISC1 gene function in neurodegenerative and neuropsychiatric disorders (such as schizophrenia, Parkinson’s disease, and Alzheimer’s disease), our findings could be considered proof-of-concept for a new treatment strategy of these diseases." (PMID 28198409, 2017).
schizophrenia (continued). "However, to our knowledge, there is no study of BACE1-dependent NRG1 cleavage activity in living patients with schizophrenia." (PMID 28993723, 2017). "However, in the current study we were unable to compare individuals with and without treatment-resistant schizophrenia and as such the ability of these NRG1 isoforms to identify treatment-resistant schizophrenia patients remains to be confirmed." (PMID 29225331, 2017). "Furthermore, within the patients with schizophrenia significant negative correlations between age of onset and NRG1 EGFα (r = −0.37, Praw = 0.002, PB-H = 0.02) and EGFβ (r = −0.36, Praw = 0.001, PB-H = 0.02) expression were detected." (PMID 29225331, 2017). "For example, genes involved in the neuregulin 1–ErbB4 signaling pathway, including DOCK7, EGFR, PTPRZ1 and the key regulator ERBB4,45, 46, 47 were downregulated in undifferentiated and disorganized schizophrenia, while they were upregulated in paranoid schizophrenia." (PMID 28809853, 2017). "However, the specific mechanism of how impaired NRG-1 signaling is involved in the etiology of schizophrenia has not been fully elucidated." (PMID 27057274, 2016). "Likewise, both NRG1 and its receptor ERBB4, which have been posited as promising candidates for schizophrenia as resulting from next-generation sequencing analyses, enhance synchronized oscillations of neurons in the prefrontal cortex, known to be reduced in schizophrenia, via inhibitory synapses." (PMID 27601987, 2016). "Lack of BACE1 processing of NRG1 has been proposed to be responsible for the hyperactivity and schizophrenia endophenotypes, spine density reduction, myelination deficits in central and peripheral nervous system and deficits in formation and maturation of muscle spindles observed in BACE1 null mice." (PMID 27192432, 2016). "The results showed the top five associated SNPs with CSS of ERBB4, NRG1 and COMT respectively, while none of the SNPs of schizophrenia associated genes COMT, ERBB4 or NRG1 was satisfied the criteria of GWAS significance threshold (Bonferroni correction P < 0.05/498,648, or i.e., ~1.0 × 10−7)." (PMID 26242244, 2015). "Moreover, our study suggests that schizophrenia linked cSNPs in TM domain of NRG1 and mutations in APH1B gene may contribute to the alteration of dendritic spines density observed in schizophrenia, linking APH1B and NRG1 misprocessing firmly to this disorder." (PMID 24891237, 2014). "In essence, the Neuregulin-1 gene and the molecular cascade NRG-1-ERB are assuming a central role among the variables that participate in the consolidation of schizophrenia’s endophenotype, while being independently related to the glutamatergic and the connectivity WM hypothesis." (PMID 22942875, 2012). "Moreover, in genome-wideassociation studies (GWAS) of Caucasians with schizophrenia or bipolar disorder,neither NRG1 nor ERBB4 have featured among the tophits in the original studies or in subsequent meta-analyses." (PMID 21637803, 2011). "However, some studies have failed to confirm the roleof NRG1 gene in the pathogenesis of schizophrenia." (PMID 23508206, 2011). "Furthermore, NRG1 is involved in the mechanisms by which NRDC controls myelin sheath formation, and one study proposed that NRG1 may be involved in the pathogenesis of schizophrenia." (PMID 38694089, 2024). "In summary, this study suggests chronic adolescent CBD does not limit the development of schizophrenia-relevant behaviors in a Nrg1 mouse model in young adulthood, and may therefore not be a potent preventative therapeutic candidate for patients harboring this mutation." (PMID 36406747, 2022). "Nevertheless, given the fact that the NRG1 – ERBB4 signaling has multiple effects in nervous system development (including neuronal migration and modulation of neurotransmission), this pathway may play a role in schizophrenia pathogenesis through other mechanisms aside from OMR effects." (PMID 24478629, 2014).